MIATNB (MIAT neighbor)
Gene: Long non-coding RNA gene on chromosome 22 (26,646,363 to 27,004,694, forward strand). Ensembl gene ENSG00000244625.
Diseases named in the same sentence as MIATNB in open-access papers:
MIATNB is named in the same sentence as 2 diseases in open-access papers, as found by Europe PMC text mining. Sharing a sentence is not in itself a finding about the gene and the disease. The quoted sentences say what the papers report.
lymphoma (2 papers, 2024). A malignant (clonal) proliferation of B- lymphocytes or T- lymphocytes which involves the lymph nodes, bone marrow and/or extranodal sites. "Similarly, MIATNB and TXK loci hypomethylated in normal T-cells gained methylation in all tested lymphomas." (PMID 38464090, 2024).
bacteremia (1 paper, 2022). "We identify SNPs within the genes CAPN14 and MIATNB as having P < 10−5 for association with development of enteric fever symptoms or bacteremia following exposure." (PMID 35254093, 2022). "While the study was underpowered to detect any single nucleotide polymorphisms (SNPs) significant at the whole-genome level, two SNPs within CAPN14 and MIATNB were identified with P < 10−5 for association with development of symptoms or bacteremia following oral S. Typhi or S. Paratyphi A challenge." (PMID 35254093, 2022).